FURIN (furin, paired basic amino acid cleaving enzyme)
Diseases named in the same sentence as FURIN in open-access papers (continued):
Sharing a sentence is not in itself a finding about the gene and the disease.
coronary artery disease (3 papers, 2021 to 2024). "Through genetic association analyses, we previously identified FURIN as a gene candidate associated with coronary artery disease in humans." (PMID 38607027, 2024). "Previously, we identified FURIN as a coronary artery disease-associated gene candidate based on a genetic association analysis of the CardiOgram cohort." (PMID 38607027, 2024). "The results of our study suggest that DNA methylation inhibits FURIN expression and that the coronary artery disease-predisposing variant rs17514846 modulates FURIN expression and monocyte migration via an allele-specific effect on DNA methylation." (PMID 37443715, 2023). "Genome-wide association studies have revealed an association between the genetic variant rs17514846 in the FURIN gene and coronary artery disease." (PMID 37443715, 2023).
esophageal cancer (3 papers, 2021 to 2025). A primary or metastatic malignant neoplasm involving the esophagus. "We observed a significantenrichment of PCSK6, PCSK9,MBTPS1, and FURIN mRNAs in the tumor tissue,which may be indication of the involvement of these PCs in the development andprogression of esophageal cancers." (PMID 40264581, 2025). "Further, CTSL, FURIN, NRP1 and SCARB1 gene expression levels were significantly higher in esophageal carcinoma (ESCA) samples in comparison to their normal matches." (PMID 35970857, 2022).
hepatocellular carcinoma (3 papers, 2015 to 2021). A malignant tumor that arises from hepatocytes. "In hepatocellular carcinoma patients, high FURIN expression even predicts a better postoperative disease-free survival." (PMID 26137475, 2015). "This is in contrast to other tumor types either where FURIN expression predicts a better postoperative disease-free survival such as in hepatocellular carcinoma or where FURIN inhibition can delay the tumorigenic process (salivary gland tumors, skin cancer)." (PMID 26137475, 2015). "SNP rs4932178 in the promoter of FURIN has been reported to influence FURIN expression in hepatocellular carcinoma cell lines." (PMID 26137475, 2015). "Interestingly, hypoxia can increase FURIN levels in HepG2 human hepatoma cells through hypoxia-inducible factor 1 (HIF1)." (PMID 34155192, 2021). "Thus, depending on the cancer type FURIN inhibition is either beneficial (salivary gland tumors, skin cancer) or disadvantageous (hepatocellular carcinoma) or has no clear effect (CRC) on the tumorigenic process." (PMID 26137475, 2015).
lung adenocarcinoma (3 papers, 2021 to 2023). A carcinoma that arises from the lung and is characterized by the presence of malignant glandular epithelial cells. "FURIN is also strongly associated with carboxypeptidase D (CPD), recently reported to be required for pro-IGF1R maturation in lung adenocarcinoma." (PMID 35768873, 2022). "In this research, samples of lung adenocarcinoma were interrogated with TME-related genes, among which high expression of PLK1, LDHA, FURIN, FSCN1, and RAB27B was correlated with poor OS, while high expression of MS4A1 was correlated with longer OS compared with the MS4A1 low expression." (PMID 37604869, 2023).
melanoma (3 papers, 2020 to 2025). A malignant, usually aggressive tumor composed of atypical, neoplastic melanocytes. "In addition to IGF1R itself, gene encoding the FURIN protease, which is required for surface presentation of IGF1R, also had a higher essentiality in NRAS‐mutant melanoma cell lines compared cells with WT NRAS." (PMID 33073517, 2020). "Other significantly reduced proteins include TRAIL, TGFR-2, ANXA1, SPARC, FURIN, GPNMB, and ERBB2, all of which play roles in melanoma progression, immune modulation, or resistance to targeted therapies." (PMID 40725203, 2025). "More importantly, the associations explored in detail in this study such as the essentiality of SRF in skin and dependence of NRAS‐mutant melanoma on IGF1R and FURIN hold true in the integrated data set and with even higher confidence suggesting that these are indeed robust associations." (PMID 33073517, 2020).
Obesity (3 papers, 2021 to 2022). Accumulation of substantial excess body fat. "The GTEx track indicates FURIN has the highest median expression in the liver, followed by the pancreas (organs directly relevant to T2D and obesity pathogenesis), whereas FES has the highest median expression in the spleen followed by the lungs." (PMID 35884374, 2022).
type 2 diabetes (3 papers, 2022 to 2025). "Moreover, FURIN, ASGR1, SORT1, TFPI, PGF, F2R, and EFNA1 were also associated with SBP, adiposity, and type 2 diabetes." (PMID 37940228, 2023). "A genome-wide DNA methylation analysis of human pancreatic islets from type 2 diabetes identified 1,649 CpG sites and 853 genes with differential DNA methylation, but none was related to the FURIN gene." (PMID 35399937, 2022).
colon carcinoma (2 papers, 2015 to 2025). "It has been reported that FURIN inhibition in human colon cancer cell lines inhibits the metastatic potential of those cell lines." (PMID 26137475, 2015). "Since, FURIN inhibition in human colon cancer cell lines has previously been shown to repress tumor metastases, association between FURIN gene expression levels and postoperative relapse-free survival was also investigated." (PMID 26137475, 2015). "Additionally, CNV analysis indicated a significant increase in the proportion of CNVs for CHRNA4 and USP42 in colon cancer, while an increase in CNVs for FURIN and FES was noted in rectal cancer." (PMID 40426913, 2025). "Therefore, we have examined whether or not FURIN expression by itself is linked with relapse-free survival in this group of 688 patients with colon cancer." (PMID 26137475, 2015). "We have also studied whether or not FURIN expression by itself has a predictive outcome in colon cancer." (PMID 26137475, 2015).
Glucose intolerance (2 papers, 2021 to 2022). Glucose intolerance (GI) can be defined as dysglycemia that comprises both prediabetes and diabetes. "Finally, we previously found that FURIN deficiency in pancreatic β cells leads to severe glucose intolerance caused by altered lysosomal acidification and aberrant activation of the mTORC1/ATF4 pathway." (PMID 34198511, 2021). "Since FURIN has multiple substrates, the glucose intolerance observed in the βFurKO mice cannot automatically be attributed to lack of processing and signaling of the proIR." (PMID 34198511, 2021).
head and neck squamous cell carcinoma (2 papers, 2021 to 2022). A squamous cell carcinoma that arises from any of the following anatomic sites: lip and oral cavity, nasal cavity, paranasal sinuses, pharynx, larynx, and salivary glands. "However, the expression profiles of ACE2, TMPRSS2 and FURIN have not been comprehensively examined in normal oral mucosa (NOM) and OSCC, a major subgroup of head and neck squamous cell carcinoma (HNSCC)." (PMID 34726347, 2022).
Insulin resistance (2 papers, 2020 to 2022). Increased resistance towards insulin, that is, diminished effectiveness of insulin in reducing blood glucose levels. "In turn, impaired Ca2+ homeostasis aggravates cardiac insulin resistance through impairing FURIN-dependent processing of IR precursor." (PMID 39872684, 2022).
liver cancer (2 papers, 2021 to 2022). An epithelial or non-epithelial malignant neoplasm that arises from the liver. "Downregulated expression of FURIN mRNA in tumor tissues was also observed in liver cancer data sets, and low FURIN expression predicted poorer overall survival of patients with liver cancer." (PMID 35668069, 2022).
periodontitis (2 papers, 2022). An acute or chronic inflammatory process that affects the tissues that surround and support the teeth. "Other than ACE2, BMAL1, CD147, FURIN, and TMPRSS2, more genes, including CD26(DPP4), IFITM3, HLA, ABO, SLC6A20, GSTT1-M1, and DBP, have also been implicated in SARS-CoV-2 and periodontitis." (PMID 36366382, 2022). "In the present study, five genes were envisaged where BMAL1 is found to be downregulated, and ACE2, CD147, FURIN, and TMPRSS1 are upregulated in periodontitis conditions and the SARS-CoV-2 infection." (PMID 36366382, 2022). "ACE2, TMPRSS2, FURIN, and CD147, which are SARS-CoV-2 primary receptors and co-receptors, are overexpressed in the periodontal tissues of periodontitis patients, presenting with inflammation, periodontal pathogens, and damage-induced pyroptosis." (PMID 36366382, 2022). "Therefore ACE2, TMPRSS2, FURIN, CD147, and BMAL1 are the crossroads between SARS-CoV-2 and Periodontitis genes." (PMID 36366382, 2022).
prostate carcinoma (2 papers, 2006 to 2022). A carcinoma that arises from epithelial cells of the prostate gland. "Considering TMPRSS2 is mainly expressed in prostate cancer, we conclude that CTSL mutations primarily correlated with FURIN expression, which might further regulate SARS-CoV-2 entry in cancers." (PMID 35414771, 2022). "Thus, overexpression of genes including CX3CL1, FURIN and MTLG was associated with poor prognosis in breast cancer patients but a favourable outcome in prostate cancer patients." (PMID 17183660, 2006).
psoriasis (2 papers, 2020 to 2023). An autoimmune condition characterized by red, well-delineated plaques with silvery scales that are usually on the extensor surfaces and scalp. "Comparative analysis of gene expression revealed that ACE2 and FURIN, which are genes significantly associated with SARS-CoV-2 infection, are upregulated in psoriasis patients, and 48 of 161 genes that are upregulated in the lungs of COVID-19 patients are also positively regulated in psoriasis." (PMID 38029150, 2023). "We also observed an expansion of regulatory T cells in three of five patients with psoriasis, and an additional population of T cells characterized by expression of SESN3, a marker of T cell senescence, SATB1, and FURIN." (PMID 33053333, 2020).
rheumatoid arthritis (2 papers, 2020 to 2023). A chronic, systemic autoimmune disorder characterized by inflammation in the synovial membranes and articular surfaces. "However, the role of FURIN in rheumatoid arthritis (RA) remains unknown." (PMID 32840921, 2020).
adenoma (1 paper, 2021). A neoplasm arising from the epithelium. "Finally, by performing an in silico analysis, we describe the mRNA expression of ACE2, TMPRSS2 and the genes encoding their co-receptors CTSB, CTSL and FURIN in normal adrenal and adrenocortical tumors (both adenomas and carcinomas)." (PMID 34594302, 2021).
aneurysm (1 paper, 2024). Bulging or ballooning in an area of an artery secondary to arterial wall weakening. "Here, FURIN was tested as aneurysm predisposition gene given its role as proprotein convertase in pro-TGF-β maturation." (PMID 38636100, 2024). "This is the first report that FURIN is a genetic predisposition for aneurysms." (PMID 38636100, 2024). "Of the eleven unrelated patients with the FURIN R745Q variant, six reported familial aneurysms." (PMID 38636100, 2024). "The proprotein convertase FURIN, which functions include TGF-β maturation, was identified as a novel genetic aneurysm predisposition and was shown to be modulated by the individuals genetic background." (PMID 38636100, 2024). "The study population size did not allow identification of the factors contributing to the polygenic effect of FURIN variants on AA, such as variants in other, aneurysm or TGF-β pathway genes, or genes that have not yet been associated with aneurysms." (PMID 38636100, 2024).
aortic aneurysm (1 paper, 2024). A ruptured aneurysm located in the wall of the proximal portion of the descending aorta proceeding from the arch of the aorta. "Rare FURIN variants were detected by whole-exome sequencing of 781 unrelated aortic aneurysm patients and affected relatives." (PMID 38636100, 2024). "This gene was selected as a candidate gene for AA based on the biological effect of FURIN on pro-TGF-β maturation and subsequent TGF-β signalling, a key signalling pathway associated with aortic aneurysm." (PMID 38636100, 2024).
Arthritis (1 paper, 2020). Inflammation of a joint. "Additionally, a positive feedback loop between FURIN and TGF‐β1 has been reported in synoviocytes, which upregulates “A disintegrin and metalloprotease with thrombospondin motif‐4” (ADAMTS‐4); this eventually leads to the destruction of arthritis." (PMID 32840921, 2020).
cervical squamous cell carcinoma (1 paper, 2021). A squamous cell carcinoma arising from the cervical epithelium. "FURIN acted as a risk factor in cervical squamous cell carcinoma (CESC, N = 304, p = 0.0073), LUAD (N = 504, p = 0.0015), glioblastoma multiforme (GBM, N = 160, p = 0.0059), and LGG (N = 509, p < 0.0001)." (PMID 33968987, 2021).
cholangiocarcinoma (1 paper, 2021). A carcinoma that arises from the intrahepatic biliary tree (intrahepatic cholangiocarcinoma) or from the junction, or adjacent to the junction, of the right and left hepatic ducts (hilar cholangiocarcinoma). "The results revealed that FURIN was highly expressed in 21 types of cancer, except cholangiocarcinoma (CHOL), lung squamous cell carcinoma (LUSC), and rectum adenocarcinoma (READ)." (PMID 33968987, 2021).
chronic obstructive pulmonary disease (1 paper, 2025). A chronic and progressive lung disorder characterized by the loss of elasticity of the bronchial tree and the air sacs, destruction of the air sacs wall, thickening of the bronchial wall, and mucous accumulation in the bronchial tree. "The elevated expression of ACE2, TMPRSS2, and FURIN in adults can be partially attributed to factors such as smoking and chronic obstructive pulmonary disease (COPD)." (PMID 40370452, 2025).
colorectal adenocarcinoma (1 paper, 2022). The most common type of colorectal carcinoma. "Finally, ACE2 and FURIN expression was also observed in colorectal adenocarcinoma metastasis in the lung." (PMID 36077610, 2022).
colorectal tumor (1 paper, 2015). "Indeed, FURIN inhibition in human colorectal tumor cells repressed tumor metastases via inhibition of IGF1R processing in mouse models." (PMID 26137475, 2015).
coronary atherosclerosis (1 paper, 2023). Atherosclerosis of the coronary vasculature. "A recent study showed that FURIN SNP rs17514846 was associated with an increased risk of early‐stage coronary atherosclerosis in human cardiac specimens." (PMID 37147786, 2023).
diffuse large B-cell lymphoma (1 paper, 2021). "In contrast, FURIN expression was negatively related to MSI in lymphoid neoplasm diffuse large B-cell lymphoma (DLBC), HNSC, PAAD, READ, skin cutaneous melanoma (SKCM), and THCA." (PMID 33968987, 2021).
female infertility (1 paper, 2017). Diminished or absent ability of a female to achieve conception. "Taken together, our data highlight the importance of FURIN in follicle development beyond the early secondary follicle stage and indicate that compromised FURIN function leads to follicular dysplasia and female infertility in mice." (PMID 28569793, 2017).
gastric cancer (1 paper, 2015). A primary or metastatic malignant neoplasm involving the stomach. "PCR result confirmed the high expression of FURIN in gastric cancer cell lines." (PMID 26036259, 2015).
head and neck cancer (1 paper, 2011). A primary or metastatic malignant neoplasm affecting the head and neck. "For example, FURIN is co-expressed with its target molecule VEGF-C in head and neck cancer, and some targets, like TGFβ-1, are even known to create a feed-forward mechanism by enhancing the expression of their converting enzyme (FURIN)." (PMID 22185580, 2011).
hypotension (1 paper, 2019). "Therefore, we examined associations among FURIN variants and the immediate blood pressure (BP) response to bouts of aerobic exercise, termed postexercise hypotension (PEH)." (PMID 30706700, 2019).
idiopathic pulmonary fibrosis (1 paper, 2022). Idiopathic pulmonary fibrosis (IPF) is a nonneoplastic pulmonary disease that is characterized by the formation of scar tissue within the lungs in the absence of any known cause. "FURIN is the target of one approved drug, pirfenidone, which is indicated for treatment of idiopathic pulmonary fibrosis." (PMID 36207451, 2022).
Iron deficiency (1 paper, 2022). "Iron deficiency also upregulates FURIN transcription through stabilization of HIF-1α, whereas iron overload inhibits furin expression in a non-HIF-1α-dependent manner." (PMID 35996194, 2022).
myocardial infarction (1 paper, 2020). Gross necrosis of the myocardium, as a result of interruption of the blood supply to the area, as in coronary thrombosis. "miR-24 showed protective features against myocardial fibrosis following myocardial infarction, which was dependent on the inhibitive effects on its target gene FURIN, suppressing the TGF-β signaling pathways." (PMID 33569393, 2020).
osteoporosis (1 paper, 2022). A condition of reduced bone mass, with decreased cortical thickness and a decrease in the number and size of the trabeculae of cancellous bone (but normal chemical composition), resulting in increased fracture incidence. "Another differentially expressed gene, FURIN, was reported as a hub gene in postmenopausal women with low BMD, as indicated by the analysis of regulatory patterns of genes potentially associated with osteoporosis risk uncovered using Bayesian network analysis." (PMID 35580864, 2022).
pancreatic cancer (1 paper, 2021). "AKT1 with TMPRSS2 and FURIN were positively correlated in all contexts except for pancreatic cancer and healthy pancreas, respectively." (PMID 33796097, 2021). "FURIN and MYC were positively associated with healthy tissues and pancreatic cancer." (PMID 33796097, 2021). "FURIN expression was not correlated with DPP4 except for pancreatic cancer, where a negative correlation was found." (PMID 33796097, 2021). "However, FURIN positively acted with MYC in pancreatic cancer, but not in the mixed cancer dataset." (PMID 33796097, 2021).
sarcoma (1 paper, 2021). A usually aggressive malignant neoplasm of the soft tissue or bone. "As for cancers, several studies have found that FURIN is expressed in various cancers and sarcomas." (PMID 33968987, 2021). "According to this study results, the FURIN expression was positively related to MSI in CESC, COAD, KIRC, LUSC, and sarcoma (SARC)." (PMID 33968987, 2021).
Sepsis (1 paper, 2025). Sepsis is defined as life-threatening organ dysfunction caused by a dysregulated host response to infection. "The relative expression levels of GNMT, SEMA4B, FURIN, and RNASE2 were significantly lower in the sepsis group than those in the control group." (PMID 40526611, 2025).